GZMB (granzyme B)
Diseases named in the same sentence as GZMB in open-access papers (continued):
Sharing a sentence is not in itself a finding about the gene and the disease.
tumor (continued). "Cisplatin-triggered ferroptotic tumor cells reprogram TANs toward an N1-like phenotype, characterized by the upregulation of cytotoxic effectors such as TNF-α, granzyme B, and NE, as well as chemokines and cytokines including CCL2, CCL3, CXCL9, CXCL10, CXCL11, IL-12A, and IL-12B." (PMID 40805288, 2025). "Additionally, we further explored the spatial transcriptomics data by performing spatial colocalization analysis between the CD8+ T cell marker gene (GZMB), the macrophage marker gene (CD68) and the tumour cell marker gene (CEACAM5)." (PMID 40770837, 2025). "Since exhausted PD-1+Tim3+CD8+ T cells are unable to produce effector cytokines, such as GzmB and IFN-γ, this insufficiency may impair anti-tumor immunity." (PMID 41225628, 2025). "Tumor lysates from ZT2 also contained higher concentrations of TNF-α, granzyme B, and IFN-γ." (PMID 41279119, 2025). "This approach has been demonstrated to enhance CD107a expression (a marker of degranulation), as well as secretion of effector molecules, such as IFN-γ and granzyme B, by both CAR T-cells and endogenous tumor-specific T-cells, suggesting a broader restoration of anti-tumor immunity." (PMID 41019052, 2025). "Despite the presence of a high percentage of activated CD8+ Tconv cells capable of producing high levels of granzyme B, we did not observe any effect of 2B010 treatment on tumor growth." (PMID 40632611, 2025). "These cells retain their cytotoxic potential and can quickly respond to tumor antigens by producing effector cytokines such as IFN-γ and granzyme B. Depletion of CD103+ TRM cells in murine RCC models leads to accelerated tumor growth, highlighting their vital role in controlling tumor progression." (PMID 40066439, 2025). "This decline may reflect active anti‐tumor effector responses by CD8+ T cells, as evidenced by changes in effector cytokines, such as Granzyme B and IFN‐γ." (PMID 41394962, 2025). "Tumor NK cells downregulated canonical NK activation markers, such as FASLG, TNFSF10, KLRK1, GZMB, and KLRD1, the latter having both inhibitory and activator capabilities but being a marker of favorable prognosis in human cancers if present in either the serum or tumor." (PMID 41208961, 2025). "Furthermore, flow cytometric analysis of tumor-infiltrating lymphocytes revealed that Vin-induced increases in CD8+ T cell infiltration, as well as the proportions of GZMB+ and IFNγ+ CD8+ T cells, were abolished in both ATF3- and IL-24-deficient tumors." (PMID 40866941, 2025). "When NK cells are activated, they produce granzyme B, and mHSP70 facilitates the uptake of granzyme B by HSP70-positive tumor cells in a nonperforin-dependent manner." (PMID 39911383, 2025). "Additionally, IHC revealed that the combination of anti-PD-1 and PRMT5i synergistically reduced Ki-67 levels in Renca tumor cells while increasing markers of tumor-infiltrating immune cells, including CD3, CD8a, and granzyme B." (PMID 40756764, 2025). "Furthermore, we also found in the TC‐1 transplantation tumor mouse model, where the percentage of CD8+PD‐1+Tim‐3+ T cells infiltrated within tumor tissues significantly decreased after receiving CX4945, whereas that of IFN‐γ+GzmB+ T cells significantly raised." (PMID 40013761, 2025). "Finally, CD4+ T cell depletion resulted in a strong upregulation of PD-1 on tumor-infiltrating CD8+ T cells and defects in the generation of granzyme B+ cytotoxic CD8+ T cells upon treatment." (PMID 40460830, 2025). "In vivo antitumor efficacy was evaluated in LLC tumor-bearing mice through measurement of tumor growth inhibition, serum cytokine levels (IFN-γ and IL-4) by ELISA, and expression levels of IFN-γ and granzyme B (GZMB) within tumor tissues via immunohistochemistry." (PMID 40872601, 2025). "Our analysis revealed significant correlations between GZMA, GZMB, GZMK and PRF1 expression and cytotoxic T cell infiltrates across various cancer types, underscoring the crucial roles of these genes in modulating the tumor microenvironment." (PMID 40002821, 2025).
tumor (continued). "CY12-RP2 treatment significantly increased the density of tumor-infiltrating lymphocytes (p < 0.001), as evidenced by expansions in CD3+ T cells and prominent elevations in Granzyme B+CD8+ cytotoxic T lymphocytes (72.4% in CY12-RP2–treated mice vs 41.8% in controls; p < 0.01)." (PMID 41573582, 2025). "Similarly, knockdown of PRDX1 in RAW264.7 augmented the cytotoxicity of tumor‐infiltrating CD8+ T cells as shown by enhanced expression of TNF‐α and GzmB, concurrent with reduced expression of PD‐1." (PMID 41306557, 2025). "Additionally, neutrophils 4 can induce apoptosis in tumor cells through TRAIL and granzyme B, further inhibiting tumor growth." (PMID 39960903, 2025). "Notably, granzyme B further contributed to pyroptosis via cleavage of GSDME, creating a feedforward loop that amplified tumor cell death." (PMID 41239499, 2025). "In order to know the association between tumor burden and immune function in HIV-HL patients, we tested the expression of GZMB in HIV-HL patients with or without bulky disease." (PMID 40969752, 2025). "Tumor cell killing was accompanied by elevated expression of activation markers (i.e., CD69) and robust production of effector cytokines (i.e., IFN-γ) and cytotoxic molecules (i.e., Perforin and Granzyme B)." (PMID 40885188, 2025). "Flow cytometry analysis of implanted tumors in immunocompetent mice showed that the depletion of MNX1 increased CD8+ T cell infiltration as well as IFN‐γ and GzmB production, indicating that MNX1 ablation activates T cell anti‐tumor immunity, thereby further inhibiting tumor growth." (PMID 39912421, 2025). "We demonstrate that SLC7A5 deletion affected T cell activation, expansion and survival, and reduced IFNγ and granzyme B expression, thus controlling aGVHD, but without effect on tumor growth." (PMID 40399490, 2025). "For cohorts with emergent MCL-1 compensation in dynamic BH3 profiling, the cellular product can be upgraded to co-deliver NOXA (or granzyme B-NOXA fusions) or it can be combined with transient, tumor-confined MCL-1 antagonists while maintaining BCL-xL targeting." (PMID 41280927, 2025). "In addition to improved phenotypes and tumor-killing efficiency, hypoxia-conditioned PIM3 KO CAR-T cells also secreted more IFN-γ, TNF-α, and granzyme B after being stimulated with tumor cells." (PMID 41199316, 2025). "When NKG2D ligands bind to NKG2D on NK cells, they activate downstream cytotoxic signalling pathways (e.g. PI3K/Akt and MAPK), thereby promoting the release of granzyme B and perforin, as well as the secretion of IFN-γ, which together mediate the killing of tumour cells." (PMID 41429765, 2025). "The proportion of the cytotoxic molecules IFN-γ and Granzyme B in CD8+T cells was higher in the knockout group than in the control, suggesting that RBMX knockout in tumor cells may influence CD8+T cell activity via cellular interactions." (PMID 40941025, 2025). "Additionally, the number of effector T cells expressing perforin, IFN‐γ, granzyme B, and TNF‐α were markedly reduced in the YP‐treated tumor microenvironment." (PMID 40108893, 2025). "For instance, in human colorectal tumours, the density of T cells (CD3, CD8, GZMB and CD45RO expression) within the tumour centre and invasive margins indicates a strong or weak adaptive immune response in situ, which is associated with tumour recurrence and patient survival." (PMID 39924620, 2025). "In the tumor tissues of the Hepa1-6 KO cells, the number of Foxp-3+ Treg cells decreased, while the number of granzyme B (GZMB)+ T cells increased without upregulating exhaustion markers such as PD-1 and TIM-3." (PMID 40139191, 2025). "Anti-PD1 and ciprofloxacin co-treatment induced CD8+ T cells granzyme B expression in the tumor but not in the spleen." (PMID 40643531, 2025). "Both HTL lines secreted granzyme B in response to HLA-DR-matched tumor cell lines, but not in HLA-DR-mismatched lines." (PMID 40723210, 2025).
tumor (continued). "These tumor-infiltrating iNKT cells exhibit an activated phenotype, characterized by CD69 and FasL expression, and production of effector molecules such as IFN-γ and Granzyme B." (PMID 40718496, 2025). "Knockdown of GZMB in ARCaP-M did not alter the expression of E-cadherin, N-cadherin, or vimentin but significantly diminished the invasive capacity of the tumor cells." (PMID 41567188, 2025). "GZMB and PRF1 showed consistently elevated expression in tumor samples compared to normal tissues across several cancers, such as BRCA and KIRC, suggesting their role in tumor immune activity." (PMID 40002821, 2025). "On the other hand, T cell-derived granzyme B activates caspase-6 to cleave GSDMC, implying that combining PARPi with immune checkpoint inhibitors could synergistically amplify tumor clearance." (PMID 41291696, 2025). "Additionally, this triple therapy increased the frequency of T-bet + CD8 + tumor-infiltrating lymphocytes (TILs) within the tumor microenvironment (TME), enhanced the frequency of CD4+ ICOS+ T cells, promoted granzyme B production, and reduced PD-1 expression." (PMID 41024300, 2025). "Given the increased expression of GzmB, IFNγ and TNFα by M002-treated CD4+ T cells, and their tumor reactivity, we next determined if these CD4+ T cells were capable of mediating killing of tumor cells beyond their conventional helper activity." (PMID 39885128, 2025). "The ability of ECT to release tumor antigens and DAMPs may functionally resemble that of in situ vaccination, as supported by the increased CD8+ lymphocyte infiltration and granzyme B activity in treated tumors." (PMID 41514601, 2025). "The antitumor efficacy of MUC28z CAR-T cells has been validated both in vitro and in vivo, showing increased expression of CD25, CD11c, and PD-1, along with decreased levels of CXCR4 and CD62L, significant tumor growth reduction, and enhanced production of IFN-γ and GZMB." (PMID 40281554, 2025). "In instances, tumour‐bearing mice being sensitive to anti‐PD1 antibody were administered with anti‐PD1 therapy and subsequently occurred to relapse, a compromised immune status was observed, characterized by diminished CD8+, CD4+ and GZMB+ levels." (PMID 40356247, 2025). "In addition, immunohistochemical analysis revealed that tumor cells were positive for CD3, CD43, CD56, TIA1, granzyme B, CD2, CD4, and CD7." (PMID 40433378, 2025). "Compared with CAR-NK cells co-expressing IL-15, CAR-NK cells co-expressing IL-21 exhibited significantly increased IFN-γ, TNF-α and Granzyme B production, as well as degranulation, in response to CD19+ Raji lymphoma cells, resulting in enhanced cytotoxic activity upon repetitive tumor stimulation." (PMID 40176196, 2025). "Consistently, they expressed the anti-tumor effectors IFN-γ, granzyme B, and TRAIL." (PMID 39835538, 2025). "Surprisingly, the knockdown of DDR1 further augmented the tumor cell immunogenicity induced by CIR, accompanied by increased intratumoral CD8 + T cell infiltration, Granzyme B and IFN-γ production, indicating an enhancement in the killing capacity of immune cells." (PMID 40993737, 2025). "The perforin and granzyme B concentrations in the NKG2D CAR-T coculture system were elevated following pretreatment of ESCC cells with increasing doses of irradiation, which was in line with increased tumor cell lysis." (PMID 40510363, 2025). "Additionally, we observed a notable elevation of the secretion of key inflammatory cytokines and effector molecules within the tumor, including TNF‐α, Granzyme B, and IFN‐γ, suggesting the activation of anti‐tumor responses." (PMID 39761175, 2025). "Notably, granzyme B also facilitates the cleavage of GSDME into its active N-terminal fragment (N-GSDME), amplifying pyroptosis in tumor cells." (PMID 41239499, 2025).
tumor (continued). "In E7GRG + 2’-3’cGAMP+CpG-C-treated tumor-bearing mice, the tumor growth was markedly suppressed, accompanied by the enhanced lymphocyte proliferation response, Th1 cytokine profile, CD8+ T-cell responses, granzyme B production, and antibody responses." (PMID 41142804, 2025). "Upon activation, they produce IFN-γ, granzyme B, and TNF and can contribute to tumor control." (PMID 40660400, 2025). "High GZMB expression in HNSCs was positively correlated with higher TMB values, suggesting that such tumor may be more amenable to immunotherapy." (PMID 40766321, 2025). "Meanwhile, we evaluated the correlation between the expression levels of Granzyme B and Perforin in human tumor specimens post‐RT and their levels in both tumor and nontumor cells pre‐RT." (PMID 39976106, 2025). "The increase in granzyme B, one of the key molecules in cell killing action, and TNF and IFN-γ, which are potent immune activators, implies that the efficacy of T cells against tumor cells is significantly enhanced." (PMID 39941980, 2025). "Additionally, increased quantities of the CD8+ cytotoxic lymphocytes and cytokines, such as GZMB and the IFN-γ, were released from the tumor microenvironment, contributing to tumor cell destruction." (PMID 39690423, 2024). "In addition, the itaconate derivatives-treated tumor cells also increased the intracellular GZMB and IFNγ expression, and CD25 expression on T cells in the tumor-T cell co-culture system." (PMID 39349845, 2024). "Further analysis of tumor-infiltrating transferred T cells as well as those in TDLNs at the end point revealed that the CUL5 KO T cells had significantly higher IL7R and GZMB expression levels than the NC cells." (PMID 38242867, 2024). "Previous studies reported a promotion of anti-tumor immunity of CD8+ T cells with an increased production of proinflammatory cytokines like IFN-γ, granzyme B and perforin and enhanced efficacy of chemotherapy through the production of metabolites, such as butyrate." (PMID 38650948, 2024). "Moreover, immunohistochemical analysis revealed in the HRH1 knockdown with αPD-1 group (sh2 + αPD-1), an increase in Granzyme B expression and CD8 T cell infiltration compared to other groups was observed within the tumor." (PMID 38715057, 2024). "Finally, CD137+ CD8+ T cells displayed the highest levels of the cytolytic molecules granzyme B and perforin compared with CD137− CD8+ T cells or CD137−PD-1− CD8+ T cells from tumour-bearing HIS mice." (PMID 38986249, 2024). "We demonstrate redundancy in these pathways, indicating that pursuing PI9 inhibition or overexpressing GZMB in immune therapies is not an ideal approach for tumor clearance." (PMID 38307835, 2024). "In addition to GZMB, another serine protease derived from cytotoxic lymphocytes, granzyme A(GZMA), can segment GSDMB and induce pyroptosis in tumor cells." (PMID 38304430, 2024). "We observed that GSDME could increase the infiltrations of CD8+T cells and their functions secreting more IL2, TNFα, GZMB, and PFN against tumor in human samples." (PMID 38853246, 2024). "In comparison to the adjacent non-tumor tissues, the CD56dimCD16hi NK cells within tumors showed a decrease in the expression of cytotoxic effector genes, such as PRF1 and most granzymes (GZMA, GZMH, and GZMM), except for GZMB." (PMID 38552055, 2024). "In addition, HA15 treatment also resulted in robust increase of both Granzyme B+ and IFN-γ+ CD8+T cells in TME compared with control, but the knockdown of either IRE1α or XBP1 in tumor cells significantly mitigated this facilitative effect." (PMID 38291473, 2024). "Moreover, LNP-mediated delivery of the bsAb mRNA exhibits a robust antitumor effect against multiple HER2-positive tumor cells and induces higher levels of IFN-λ and granzyme B than the direct application of the bsAb." (PMID 39066446, 2024).
tumor (continued). "Granzyme B (30 kDa) is one of the major effectors of cytotoxic T lymphocyte (CTL)-mediated cell death that is released into the extracellular space upon T-cell activation, where it penetrates target tumor cells via perforin-mediated entry." (PMID 38672273, 2024). "Indeed, xenografts from combination treatment group contained increased amounts of human tumor infiltrating CD8+ lymphocytes and GZMB+ lymphocytes." (PMID 39023171, 2024). "In aggregate, these results suggest that GZMB inhibition by PI9 does not alter the frequency or kinetics of CAR T cell-mediated killing of tumor cells." (PMID 38307835, 2024). "Similar to previous tumor findings, we also found a reduced percentage and MFI of NK cells IFN-γ, and a reduced positive percentage of granzyme B and perforin in circulating NK cells in patients with CRC, which may also favor cancer cell survival." (PMID 38806640, 2024). "Additionally, the triple therapy elevated the levels of GZMB in peripheral blood and IFN-γ in tumour tissue." (PMID 38816831, 2024). "However, on the other hand, granzyme B is also capable of inhibiting the proliferation of CD4+ and CD8+ T cells, thereby favoring tumor growth." (PMID 38927922, 2024). "Correlation analysis showed that B. thetaiotaomicron abundance positively correlated the RNA level of CD8A, GZMB, IFN-gamma and TNF, which represented the function of cytotoxic CD8+ T cells, which is essential immune cells for Immune surveillance of tumor cells." (PMID 38270111, 2024). "Further examination of the TME utilizing flow cytometry disclosed that PHA-793887 markedly augmented the secretion of cytotoxic T cell-associated cytokines, including interferon-gamma (IFN-γ), tumor necrosis factor-alpha (TNF-α), and granzyme B (GZMB), within the tumor milieu." (PMID 39676867, 2024). "Specifically, GZMB expression in the tumor decreased with RUX therapy, but not in all patients who were treated with RUX + PAC." (PMID 38297352, 2024). "Moreover, we provide the first evidence in HCC that tumor cell-extrinsic Axl expression modulates the tumor immune microenvironment by recruiting CD8+ T cells and Granzyme B+ cells." (PMID 38673795, 2024). "Notably, silencing Dusp18 resulted in a deceleration of xenograft tumor growth, accompanied by increased levels of IFN-γ and GzmB expression, and a decrease in the percentage of PD-1+, TIM-3+, and CTLA-4+ CD8+ T cells." (PMID 38992029, 2024). "Notably, blockade of VISTA showed increased apoptosis of tumour cells, as well as increased expression of IFN‐γ, GzmB and Perforin within CD8+ T cells." (PMID 38356419, 2024). "Anti-B7H4/CD3 bsAbs applied in a breast cancer humanised mouse model led to immediate and strong antitumour activity tumours and CD8 and granzyme B+ CTL infiltration into the tumour, and there were no adverse effects after long-term observation." (PMID 39061159, 2024). "Consistent with human CD8 GZMB+, the human-like CD8 GZMB+ clusters (Cluster0, 1) also had significantly higher Ctla4, Tox and Tox2 expression in the tumor environment injected with Macro CD5L+, while the expression of Pdcd1 (PD1) was not different between the two groups." (PMID 38245530, 2024). "We collected tumor tissue from the intervention and distant sides and performed flow cytometry analysis on CD8+T cells and various subtypes (Ki67+CD8+T, IFN-γ+CD8+T, PD-1+CD8+T, and Granzyme B+CD8+T cells." (PMID 38339426, 2024). "Cytokines (IFN-γ, granzyme B, perforin, and TNF-α) secreted by T cells are important for maintaining immunosurveillance, and inhibition of these cytokines can promote the growth and metastasis of tumor cells." (PMID 38340166, 2024). "Additionally, B. thetaiotaomicron-treated macrophages significantly enhanced the secretion of IFN-gamma and GZMB cytokines by CD8+ T cells, as well as improved the T cell-mediated killing of tumor cells." (PMID 38270111, 2024).